IL32 (interleukin 32)
Diseases named in the same sentence as IL32 in open-access papers (continued):
Sharing a sentence is not in itself a finding about the gene and the disease.
tumor (continued). "As such, we established a standard treatment regimen to evaluate the efficacy of IL-32 in ICB-resistant B16F10 and 4T1 as well as in highly immunogenic MC38 murine syngeneic tumor models." (PMID 32841222, 2020). "Based on the intersection of interleukin superfamily signature between human BC tissues and cell lines to exclude the tumor heterogeneity, both TNBC tissues and cell lines dominantly expressed IL1A, IL1B, IL8, and IL32." (PMID 30728901, 2019). "High aTaCC values for cofilin‐1, IL‐32, PCNA, syntenin‐1, and ribophorin‐2 suggested that these proteins were best represented with highest sequence coverage in the tumor immunopeptidomes in this cohort." (PMID 29786170, 2018). "Strategies focused on down-regulating TMEM158, Mybl1, IL32, ETS1 and PTX3 should be considered to determine their effect on TNBC tumor progression." (PMID 28966727, 2017). "Likewise, IL32 expression in Treg was identified to correlate with the impaired function of CD8+ T cell and tumor progression, in line with our investigations." (PMID 40524231, 2025). "Furthermore, activated CAFs release SDF-1/CXCL12, OPN, periostin, galectin, THBS2, MFGE8, and diverse cytokines such as IL-6 and IL-32, which promote the EMT, tumor invasion, and tumor metastasis." (PMID 40352270, 2025). "Taking advantage of the 3D hydrogel-based tumor-immune cell coculture system (3D-HYGTIC) constructed by us, we demonstrated that the PD-1-triggered increase in ADGRE5 expression was dependent upon IL32, which was suppressed by a STAT5 inhibitor." (PMID 38343549, 2024). "Furthermore, NanoString analysis revealed a parallel increase in levels of classical MHC-I and IL32, which positively correlated with the proportion of the malignant TCR clone in MF tumor skin lesions." (PMID 38272918, 2024). "A noteworthy observation was the positive correlation between the expression of classical MHC-I and IL32 in tumor skin T cells, a connection not observed in single bystander or healthy T-cell populations." (PMID 38272918, 2024). "Thus, we implanted 1 × 106 INA-6 iRFP-labelled IL-32 KO and WT cells into humanized bone scaffolds in immune compromised female RAG2−/− GC−/−mice and followed tumor growth by imaging." (PMID 35005550, 2022). "In patients MM02 IL-32 was not expressed in the bone marrow sample taken at diagnosis (MM02) but highly expressed in all the cells of the extramedullary tumor sample (MM02EM) obtained 18 months later." (PMID 35005550, 2022). "We further utilize bulk RNA-seq data and found a significant upregulation of SOX9, IL32, and SLC22A6 (PT2), and downregulation of SLC22A6/ SLC22A8 (PT1) in tumor compared to adjacent normal tissue, confirming our cell origin hypothesis on PT2 cells." (PMID 36180422, 2022). "Moreover, IL-32 expression increased the number of NK cells and CD8+ T cells in blood and recruited NK cells and CD8+ T cells in tumor tissues." (PMID 34682815, 2021). "A strong negative correlation was found between IL32 expression and tumor purity, indicating that IL32 mRNA expression in SKCM tissues is likely to have been derived from infiltrated immune cells." (PMID 34682815, 2021). "Our study demonstrated that blocking IL-32 may reduce Treg cell development, or increasing IL-32 expression may enhance cytotoxic CD8+ T cell function in the ESCC tumor immunotherapy." (PMID 34414188, 2021). "Proinflammatory cytokine interleukin 32 (IL-32) is involved in infectious diseases and cancer, but what subtypes of immune cells express IL-32 and its roles in tumor microenvironment (TME) have not been well discussed." (PMID 34414188, 2021). "Furthermore, IL-32 treatment rendered B16F10 tumors responsive to anti–PD-1 treatment and the combination significantly improved control of tumor growth compared with either monotherapy." (PMID 32841222, 2020).
tumor (continued). "Separate analysis conducted in tumors and non-cancerous adjacent tissue showed that IL32 expression significantly increased along with growing depth of tumor invasion (T stage) in ESCC patients in adjacent tissue but not in tumors: (ρ = 0.51, p = 0.036)." (PMID 33020452, 2020). "The concentration of IL-32 (protein) was determined in homogenates of patient-matched tumor and non-cancerous tumor-adjacent tissue (63 pairs) from 17 ESCC patients, 12 GC patients and 34 CRC patients using dedicated immunoassays." (PMID 33020452, 2020). "This could bring together T cells secreting notable amounts of IFNγ, TGBβ, IL32, and IL18RAP with myeloid/monocyte-derived cells in the tumor microenvironment." (PMID 33076479, 2020). "Supporting the notion, the abundance of IL32 transcripts in non-cancerous tumor-adjacent esophageal mucosa increased along with growing depth of tumor invasion." (PMID 33020452, 2020). "This may explain the previously noted positive correlation between IL-32 expression and individual genes indicative of lymphocyte infiltration, such as CD3E, CD8A, and IFNG, in bulk tumor samples." (PMID 32841222, 2020). "Both IL32 transcripts and IL-32 protein were more abundant in non-cancerous tumor-adjacent tissue from CRC patients with right-sided tumors, while interleukin tumor expression displayed a similar tendency." (PMID 33020452, 2020). "In the non-cancerous tumor-adjacent tissue, IL32 expression was significantly higher in esophageal than colorectal mucosa (by 2.4-fold) and tended to be higher in gastric as compared to colorectal mucosa (by 2.3-fold)." (PMID 33020452, 2020). "Moreover, IL-32 by promoting production of MMP2, MMP9, IL-8, and VEGF facilitates invasion as well as migration of tumor cells." (PMID 30402092, 2018). "In efforts to validate the genes and identify a reliable subset of candidate genes, the list of 21 genes were examined experimentally via PCR using MCF7 (luminal), MCF10A (triple negative, non-tumor), MDA MB468 (TNBC, basal A), (HCC70 (TNBC, lower IL32) and MDA MB231 (TNBC, higher IL32) cell lines." (PMID 28966727, 2017). "In NSCLC, IL-32 transactivates the nuclear transcription factor NF-κB, which upregulates the expression of matrix metalloproteinases (MMP-2 and MMP-9), increasing the invasion of tumor cells." (PMID 27445423, 2016). "IL32 transcripts were present in all intratumoral Th subsets, though at different levels, with the highest expression in suppressive Treg followed by Th1 Teff, but also in circulating IFNγ+CD4+ Teff (Th1) reactive to the breast tumor antigen mammaglobulin (MAMI)." (PMID 39211051, 2024). "As for the function of IL-32, we found that IL-32 knockdown could attenuate the migration but not the proliferation of ESCC tumor cells in vitro." (PMID 35428295, 2022). "IL-32 was significantly higher in the tumor nest compared with the non-cancerous tissue." (PMID 35428295, 2022). "Moreover, angiogenesis was also observed in subcutaneous tumor model injected with the IL-32 high-expression group (Data were not shown)." (PMID 35428295, 2022). "However, it is not clear yet how IL-32 contributes to the different tumor types including stromal tumor microenvironment." (PMID 35281008, 2022). "Both subsets of CD8+ T cells from tumor samples expressed higher effector genes than nonmalignant samples, including chemokines (e.g., CCL5), cytotoxicity-associated genes (PRF1, GZMA, GZMB, GZMH), and proinflammatory cytokines (e.g., IL-32)." (PMID 34921160, 2021). "IL-32 may have a contradictory role in the TME such as it promotes IFNγ expression in CD8+ T cells, which enhances the antitumor activity, but at the same time induces Foxp3 expression in CD4+ T cells, which suppresses the tumor immune response." (PMID 34414188, 2021). "IL-32 may promote CD8+ T cell IFNγ expression that enhances the antitumor activity, but at the same time induce CD4+ T cell Foxp3 expression, which could suppress tumor immune response." (PMID 34414188, 2021).
tumor (continued). "IL32 was independently and positively associated with Ki67, HIF1A, and ACTA2 and negatively with TJP1 in tumors and with IL10Ra and BCLxL in non-transformed tumor-adjacent tissue." (PMID 33020452, 2020). "Notably, as opposed to studies performed in IL-32–overexpressing mice, we did not observe any direct cytotoxicity of IL-32 to tumor cells in vitro." (PMID 32841222, 2020). "Furthermore, TCR clonality was significantly enhanced in the tumors, but not in the spleens, of mice treated with IL-32, suggesting the presence of tumor-reactive T cell clones." (PMID 32841222, 2020). "Relative IL32 expression was determined in patient-matched samples from tumor and non-transformed mucosa adjacent to tumor (52 pairs), obtained from 17 patients with ESCC, 14 with GC, and 21 with CRC using reverse-transcribed quantitative (real-time) polymerase chain reaction (RT-qPCR)." (PMID 33020452, 2020). "Finally, there appears to be a unique set of cytokines, including IL-10 and IL-32 g, which are capable of promoting PD-L1 expression on Monos but not on tumor cells, as studied in our previous report and in unpublished data." (PMID 31730010, 2019). "In the analysis around node 2, we observed enrichment of numerous immune-related genes at the starting point, such as IL32 and CEACAM7, indicating that immune regulation might play an important role in early cell state transitions and potentially participate in tumour microenvironment remodelling." (PMID 40539065, 2025). "According to these results, we speculate that T cells that express IL-32 may have a contradictory role that promotes IFNγ expression in CD8+ T cells, which enhances the antitumor activity, and induces CD4+ T cells Foxp3 expression, which suppresses tumor immune response." (PMID 34414188, 2021). "However, the differences in CCL5 and CCL4 expression between IL-32–treated tumors from WT and Batf3–/– mice were not statistically significant, suggesting that DC are not exclusively responsible for the increased tumor chemokine levels in response to IL-32 treatment." (PMID 32841222, 2020). "IL32 has one isoform, ENST00000525643.6, which was identified from all the tumor and non-malignant samples." (PMID 32732980, 2020). "IL32 expression was significantly upregulated solely in ESCC, reflecting T stage in non-transformed tumor-adjacent tissue." (PMID 33020452, 2020).
cancer (99 papers, 2001 to 2025). A tumor composed of atypical neoplastic, often pleomorphic cells that invade other tissues. "Research has shown that cancer-associated, fibroblast-derived exosomes promote the viability, migration, and invasion of GC cells by upregulating the interleukin 32/estrogen receptor 1 (ESR1) axis." (PMID 40601671, 2025). "To confirm that IL‐32 is the downstream effector of YY1‐mediated PC effects on EGFR‐mutated cancer cell sensitivity to TKI, we exposed these cells to CM from YY1‐depleted PCs in the presence of TKI drugs, with or without IL32 treatment." (PMID 39435643, 2024). "Further RT‐PCR analysis consistently indicated that IL32 was the only cytokine consistently up‐regulated in PCs when compared to EGFR‐mutated cancer cell lines or their paired primary cancer cells." (PMID 39435643, 2024). "The IC50 results indicated that the addition of IL32 increased the IC50 value of TKI drugs in EGFR‐mutated cancer cells treated with CM from YY1‐depleted PCs compared to the placebo‐treated group." (PMID 39435643, 2024). "GO enrichment analysis showed that IL32 expression was associated with cancer pathways, cytokine-receptor interactions, and NOD-like receptor signaling pathways." (PMID 38584169, 2024). "The results indicate that overexpression of IL32 has certain diagnostic value in various types of cancer." (PMID 38584169, 2024). "While less is known about IL-34, except that it can increase monocyte activity, IL-32 has been implicated in fibrosis and cancers associated with chronic inflammation, including HCC39,40." (PMID 38429349, 2024). "On the other hand, these findings are consistent with data from previous study that mutant allele T of IL-32 rs28372698 polymorphism acts as an increased risk factor to cancer." (PMID 36505098, 2022). "While IL-32 is associated with the outcome of several cancers and plays a role in both inflammatory and infectious diseases, its precise cellular source and functions within the TME remain poorly described." (PMID 32841222, 2020). "Little is known on clinical and diagnostic relevance of interleukin-32 in gastrointestinal tract (GIT) cancers." (PMID 33020452, 2020). "The diagnostic power of circulating IL-32 in distinguishing cancer patients from healthy individuals was tested using receiver operating characteristic (ROC) curve analysis." (PMID 33020452, 2020). "To comprehensively analyze the association between IL-32 expression and mature DC in cancer, we used a previously defined gene signature representing “mature DC” to score samples from all TCGA cohorts." (PMID 32841222, 2020). "Recently, several reports have clearly indicated that two single nucleotide polymorphisms (SNPs) in the IL-32 gene sequence (rs12934561 and rs28372698) were associated with cancer susceptibility (LC, GC, TC, EC, and CRC)." (PMID 33204366, 2020). "In our previous studies of the TMEs of several different cancer types, we found that elevated levels of transcripts for the cytokines IL-1a, IL-10, IL-27 and IL-32 g, in addition to IFN-g, were associated with PD-L1 protein expression." (PMID 31730010, 2019). "IL32 expression in cancer is linked to features associated with worse prognosis, including angiogenesis, invasion, and metastasis." (PMID 30953519, 2019). "It has also been reported that IL-32 was critically associated with the development of several cancers." (PMID 30486830, 2018). "Interleukin (IL)-32α, the shortest isoform of proinflammatory cytokine IL-32, is associated with various inflammatory diseases and cancers." (PMID 27589563, 2016). "In summary, this study utilized comprehensive bioinformatics analysis methods to explore the expression levels of IL32 in pan-cancer, its potential diagnostic and prognostic value, gene mutations, RNA methylation, immunoregulatory effects, and related signaling pathways." (PMID 38584169, 2024).
cancer (continued). "Based on these findings, elevated IL32 expression in pan-cancer was linked to a poor prognosis and might be a potential prognostic biomarker." (PMID 38584169, 2024). "To further dissect the underlying molecule mechanism of pericyte‐IL32 mediated TKI sensitivity in cancer cells, we performed comparative proteomics analysis of HCC827 or PC9 cells after being treated with conditioned medium (CM) from either HCC827/PC9 cells or PCs in the presence of TKI treatment." (PMID 39435643, 2024). "A systematic review revealed that the germ-line rs28372698 and intronic rs12934561 polymorphisms of IL-32 are associated with cancer development in Asian dynasty while compared to Caucasians, and the TT/TC genotypes of rs12934561 are related with a reduced cancer risk closely." (PMID 36505098, 2022). "Interestingly, IL32 secreted by cancer-associated fibroblasts, binding to β3 integrin was able to up-regulate EMT markers and increase TNBC cell invasion." (PMID 30682838, 2019). "IL-32, a novel cytokine, is associated with inflammation and cancer development." (PMID 30486830, 2018). "IL-32 has previously been implicated in inflammatory diseases and cancer, but its role in myogenesis or muscle function remains unknown." (PMID 28222718, 2017). "IL-32 is expressed in chronic inflammation-linked human cancers." (PMID 25909160, 2015). "IL-32’s biological activity depends on cell type and context, with isoform-specific variations, allowing it to either promote or inhibit cancer development." (PMID 40110195, 2025). "In some tumors, IL-32 contributes to cancer progression by modulating key signaling pathways, including NF-κB, STAT3, and MAPK." (PMID 41181127, 2025). "Recent studies have highlighted the involvement of IL-32 in cancer development, and its expression is identified in various cancers such as gastric, lung, and pancreatic cancer." (PMID 39519229, 2024). "We performed a Pearson correlation analysis of ADGRE5, CD55 and IL32 in the pan-cancer TCGA database." (PMID 38343549, 2024). "Further research is needed on the genetic alterations of IL32 as well as the relationship between RNA methylation and the expression of IL32 in cancer." (PMID 38584169, 2024). "In conclusion, our systematic study of the role of IL32 in human pan-cancer will elucidate the clinical role and potential molecular mechanisms of IL32 in pan-cancer." (PMID 38584169, 2024). "There are few reports exploring the relationship between IL-32 and cancer immunotherapy, and it is necessary to identify the function of each isoform in the cancer immune cycle." (PMID 39235457, 2024). "We investigated gene expression, genomic alterations, and survival analysis of IL32 in pan-cancer in numerous databases including TCGA, GTEx, cBioPortal, and GDC databases." (PMID 38584169, 2024). "IL-32 in cancer cells exerts anti-cancer effects by inhibiting cell growth and inducing cancer cell apoptosis." (PMID 39519229, 2024). "This research aids in better understanding the role of IL-32 in the onset and development of tumors, offering clues for the development of new cancer treatment strategies." (PMID 38584169, 2024). "We compared these results with those from cancer cells and found a specific increase in the proinflammatory factor IL32 in PCs." (PMID 39435643, 2024). "Taken together, IL-32β is the prevailing isoform of IL-32 both on the mRNA and the protein level in various T cell subsets not only in healthy individuals but also in cancer patients." (PMID 39211051, 2024). "Mechanistically, it is shown that YY1 signaling upregulates IL32 secretion in PCs, subsequently activating the β5‐integrin‐Src‐Akt pathway in EGFR‐mutated cancer cells, contributing to their TKI sensitivity." (PMID 39435643, 2024). "We also conducted a western blot analysis of IL32 expression in PCs derived from three different EGFR‐mutated NSCLC patients, as compared to cancer cell lines, confirming the up‐regulation of IL32 in all PCs." (PMID 39435643, 2024).